LSS (lanosterol synthase)
Diseases named in the same sentence as LSS in open-access papers (continued):
Sharing a sentence is not in itself a finding about the gene and the disease.
Usher syndrome type 3 (1 paper, 2024). A syndrome characterized by postlingual progressive hearing loss, abnormalities in the vestibular system, and onset of retinitis pigmentosa symptoms usually by the second decade of life. "However, bi-allelic variants in CLRN1, LSS, and TUB have been associated with AR Usher syndrome type 3, congenital cataract, or RP, respecitvely." (PMID 38785568, 2024).
viral infection (1 paper, 2025). "Genes controlling the key steps in cholesterol biosynthesis, such as FDPS, ACAT2, MVD, LSS, and FDFT1, were transcriptionally commonly suppressed upon viral infection at 48 hpi." (PMID 40857262, 2025).
cancer (15 papers, 2015 to 2025). A tumor composed of atypical neoplastic, often pleomorphic cells that invade other tissues. "Together, our data demonstrate that ATR upregulates LSS, which promotes mTORC1 activity through cholesterol in cancer cells." (PMID 40514450, 2025). "ATR activates mTORC1 by increasing phosphorylation and expression of the de novo cholesterol synthesis enzyme lanosterol synthase in cancer cells." (PMID 40514450, 2025). "Our RNA-seq analysis revealed that LSS overexpression significantly upregulates MAPK pathway genes, particularly those involved in the JNK and P38 branches, which are known to be activated in response to cellular stress and are often associated with cancer progression." (PMID 39922821, 2025). "ACSL3, AIFM2, HSD17B7, LPCAT1, LSS, PLIN3 and RAB10 were up-regulated with the progression of cancer stage of HCC patients, while CIDEB, G0S2, HSD17B13, PLIN1 and PLIN2 were down-regulated." (PMID 37464334, 2023). "2,3-oxidosqualene cyclase (OSC) referred to as lanosterol synthase (LSS), mediates cancer neovascularization and metastasis through the activation of the PI3K/Akt signaling pathway and FGF-2." (PMID 37754524, 2023). "Consistent with the ATR-LSS axis promoting mTORC1 activity via cholesterol in p16 knockdown cancer cells, knockdown or inhibition of either ATR or LSS decreased mTORC1 activity, and these effects were rescued by supplementation with either lanosterol or cholesterol." (PMID 40514450, 2025). "In addition to HMGCR, the expression of lanosterol synthase (LSS), an important enzyme for cholesterol synthesis, was abnormally reduced in cancer tissues." (PMID 38606362, 2024). "Moreover, inhibition of specific enzymes involved in cholesterol metabolism, including lanosterol synthase (LSS), farnesyl diphosphate synthase (FDPS), and squalene epoxidase (SQLE), has been shown to suppress cancer metastasis." (PMID 38762737, 2024). "It is known that lanosterol synthase (LSS) can regulate protein aggregation by effectively reducing the number and/or size of sequestosomes/aggresomes formed by endogenous proteins in the normal and cancer cells." (PMID 34440098, 2021). "Similar to LSS inhibition, inhibiting SC4MOL may aid in sensitizing cancer cells to chemotherapy." (PMID 38672427, 2024).
tumor (9 papers, 2015 to 2025). "Since LSS is an important enzyme for cholesterol synthesis, to further explore the underlying mechanism of LSS‐mediated tumor suppression, we first examined the changes in cholesterol content." (PMID 38606362, 2024). "In conclusion, our results show that LSS deficiency promotes tumor progression by establishing an OS–PDL1 axis‐dependent immunosuppressive microenvironment, indicative of LSS or OS as a potential hallmark of response to immune checkpoint blockade." (PMID 38606362, 2024). "In EC, we found that LSS overexpression drives the accumulation of these esters, further promoting tumor growth." (PMID 39922821, 2025). "We demonstrate that treating PCa cells with 433‐3β leads to decrease in CHOL levels in PCa cells in vitro and in xenograft tumor tissues of treated mice by potentially inhibiting lanosterol synthase and CYP51A1." (PMID 40007440, 2025). "We further investigated the effects of LSS overexpression and inhibition on EC cell proliferation and tumor growth in vitro and in vivo, exploring the mechanistic role of the MAPK/JNK signaling pathway in this context." (PMID 39922821, 2025). "In vivo, nude mouse xenograft experiments demonstrated that LSS overexpression significantly promoted tumor growth." (PMID 39922821, 2025). "The biological activity of tumor cell lines and tumor progression in NOD scid gamma (NSG) mice were not affected after LSS knockdown, whereas LSS deficiency obviously aggravated tumor burden in fully immunized mice." (PMID 38606362, 2024). "Notably, the tumor‐promoting effect mediated by LSS knockdown was abolished in myeloidKO mice, which suggested that macrophages and MDSCs may mediate the anti‐tumor effect of LSS." (PMID 38606362, 2024). "Furthermore, the reduction of cellular cholesterol content was also observed with LSS knockdown, indicating different enzymes or derivatives of cholesterol synthesis may have different tumor regulatory effects." (PMID 38606362, 2024). "Nevertheless, our current investigation reveals that LSS, a critical enzyme in the latter stages of cholesterol synthesis, is down‐regulated in CRC and BRCA cells and significantly promoted tumor progression and shortened patient survival." (PMID 38606362, 2024). "The upregulation of LSS not only enhances EC cell proliferation and migration but also inhibits apoptosis by activating the MAPK/JNK signaling pathway, thereby contributing to tumor growth both in vitro and in vivo." (PMID 39922821, 2025). "Given that systemic immunity is also critical for tumor progression, we also found that LSS knockdown increased the percentage of monocytes and the number of PMN‐MDSC, but did not affect M‐MDSC in the spleen, suggesting that PMN‐MDSCs are also involved in the anti‐tumor effect of LSS." (PMID 38606362, 2024).
autosomal recessive disease (1 paper, 2021). Autosomal recessive form of disease. "Thus, the studies on LSS mutations suggested that dysfunctions of LSS are far more complex and lead to autosomal-recessive diseases." (PMID 34926465, 2021).
LSS also shares sentences with these, for which no sentence is quoted: colon carcinoma (2 papers); infection (2); acute kidney injury (1); Age-related cortical cataract (1); autosomal recessive hypotrichosis (1); Cognitive impairment (1); colorectal (1); cutis laxa (1); developmental delay (1); early-onset epilepsy (1); gestational diabetes mellitus (1); Hepatic steatosis (1); hospital-acquired infection (1); Huntington disease (1); hypotrichosis 14 (1); intellectual disability syndrome (1); Lipid metabolism disorders (1); Listeria infection (1); liver cirrhosis (1); Macrocephaly (1); nephronophthisis (1); neurological disorders (1); osteosarcoma (1); Palmoplantar keratoderma (1); pancreatic adenocarcinoma (1); pancreatic ductal adenocarcinoma (1); prostate carcinoma (1); scoliosis (1); Sengers syndrome (1); Smith-Lemli-Opitz syndrome (1).
A further 2 diseases each share a sentence with LSS in 1 paper.